IL2 (interleukin 2)
Diseases named in the same sentence as IL2 in open-access papers (continued):
Sharing a sentence is not in itself a finding about the gene and the disease.
neuroblastoma (continued). "Based on these results, Dinutuximab (anti-GD2 ch14.18 antibody) in combination with IL2 and GM-CSF was approved by the United States Food and Drug Administration (FDA) in 2015 for the treatment of high-risk neuroblastoma patients." (PMID 37854601, 2023). "In contrast, circulating NK cells from patients with neuroblastoma had a high frequency of NK cells activated by IL2/15, with IL2 induced CD69 upregulation notably lower." (PMID 36276144, 2022). "Unexpectedly, CD56bright NK cells from children with neuroblastoma dramatically upregulated granzyme B expression in response to cytokine with an average of 6-fold and 9-fold increase for IL2 and IL12/15 respectively." (PMID 36276144, 2022). "The data show that while extracellular acidification rates (ECAR) were relatively low, IL2 induced higher glycolytic flux in NK cells from patients with neuroblastoma compared to healthy children." (PMID 36276144, 2022). "In a pilot trial, 13 patients with recurrent/refractory neuroblastoma were treated with hu14.18K322A, GM-CSF, IL-2, and chemotherapy combined with an infusion of haploidentical NK cells resulting in a 61.5% response rate and 38.5% had stable disease." (PMID 34199783, 2021). "Use of this strain for neuroblastoma PDX allowed the study specifically to compare NK cell-mediated ADCC due to either IL-2 or IL-15 activated NK cells." (PMID 33808071, 2021). "For patients with relapsed or refractory neuroblastoma, IL-2 should be added to dinutuximab beta, by subcutaneous injections of 6 × 106 IU/m2/day, for two periods of 5 consecutive days." (PMID 34884452, 2021). "Together, these findings led to the rationale to initiate the “phase I/II feasibility study using ch14.18/CHO antibody and subcutaneous interleukin 2 after haploidentical stem cell transplantation in children with relapsed neuroblastoma” (NCT02258815)." (PMID 34367149, 2021). "The use of anti-GD2 mAbs, although largely beneficial for neuroblastoma patients with the use of anti-GD2 mAb Dinutuximab/IL-2/GM-CSF therapy, shows toxic side-effects such as allodynia due to the expression of GD2 on peripheral nerves." (PMID 34200284, 2021). "Recent interest in the area of immunotherapy has led to the use of RA therapy in combination with anti-GD2 antibodies and IL-2, which has seen an improvement in neuroblastoma patient overall survival." (PMID 33809565, 2021). "In fact, when various cancer cell lines were studied in vitro, we found that Salmonella-IL2 invaded hepatocytes most readily when compared with hepatoma, neuroblastoma, adenocarcinoma, and osteosarcoma." (PMID 32554977, 2020). "RO6874281 is a bispecific IL2 immunocytokine which targets cancer associated fibroblasts via binding to FAP and has shown potent anti-tumor activity in melanoma, neuroblastoma and colon carcinoma models." (PMID 32722460, 2020). "The effect of the CM harvested from native hADSCs, hADSCs-BFP or hADSCs-IL2 on SH-SY5Y (neuroblastoma), PC3 (prostate cancer) and A549 (lung adenocarcinoma) tumor cell proliferation in vitro was investigated." (PMID 32560387, 2020). "However, IL-2 administered with alternating cycles of GM-CSF plus the mAb ch14.18 (dinutuximab) resulted in higher rates of event-free (66% versus 46%) and overall (86% versus 75%) survival after 2 years compared to standard therapy alone in children with high-risk neuroblastoma." (PMID 31847387, 2019). "In a separate study, 39 patients with recurrent neuroblastoma were treated with the Hu14.18-IL-2 immunocytokine—a fusion protein combining the humanized 14.18 anti-GD2 antibody with IL-2." (PMID 30384486, 2018). "A humanized antibody is used to target hu14.18-IL2, a fusion protein consisting of IL2 linked to an antibody that recognizes the GD2 disialoganglioside expressed on neuroblastoma cells." (PMID 28574434, 2017). "Using the same analysis, high expression of IL-2 correlated with better survival in the neuroblastoma patient cohort." (PMID 27477778, 2016).
neuroblastoma (continued). "For example, in neuroblastoma the combination of cytokines (IL-2+/– GM-CSF) with anti-GD2 monoclonal antibodies has been evaluated clinically." (PMID 26942051, 2016). "Several clinical studies revealed that the combination of mAb ch14.18, IL-2 and GM-CSF or variant GD2 antibody fused to IL-2 (mAb hu14.18-IL2) showed increased efficiency to achieve long-term event-free survival of neuroblastoma patients." (PMID 27716771, 2016). "Anti-GD2 mAbs combined with GM-CSF or GM-CSF and IL-2 are effective against neuroblastoma with studies planned in osteosarcoma." (PMID 26301204, 2015). "While anti-GD2 mAb alone produced some anti-tumor activity in neuroblastoma patients, combining the mAb with GM-CSF and interleukin 2 (IL2) to further activate immune effector cells enabled potent clinical anti-tumor efficacy of anti-GD2 mAb." (PMID 26284063, 2015). "As naive NK cells were shown unable to eradicate neuroblastoma cells, we additionally used NK cells that were prior stimulated with IL-2 and IL-15, similar to NK cells used in cellular immunotherapy." (PMID 26452036, 2015). "Another anti-GD2 drug, humanized 14.18-3F8 conjugated to IL-2, has shown activity in Phase II trials in children with refractory/relapsing neuroblastoma." (PMID 26587548, 2015). "As with experiments testing neuroblastoma/monocyte CM, we discovered that lenalidomide, at clinically achievable concentrations, prevented IL-6 suppression of IL-2-mediated activation of NK cell cytotoxicity, ADCC, and IFNγ secretion." (PMID 23982484, 2013). "IL-6, which is secreted by mononuclear phagocytes in response to neuroblastoma cells, and TGFβ1, which is secreted by both tumor cells and mononuclear phagocytes in response to neuroblastoma cells, suppress the activation of NK cells by IL-2." (PMID 23982484, 2013). "In summary, our study demonstrates that the microenvironmental milieu of neuroblastoma cells includes IL-6 and TGFβ1, which suppress IL-2 activation of NK cells for direct cytotoxicity, ADCC, and IFNγ secretion." (PMID 23982484, 2013). "Neuroblastoma cell/monocyte co-cultures generated CM that contained IL-6 and TGFβ1 and that suppressed IL-2 activation of NK cells for direct cytotoxicity, ADCC, and IFNγ secretion." (PMID 23982484, 2013). "CM from neuroblastoma/monocyte co-cultures contains IL-6 and TGFβ1 that suppress IL-2 activation of NK cell cytotoxicity and IFNγ secretion." (PMID 23982484, 2013). "Although the neuroblastoma/monocyte CM contained IL-6 and TGFβ1, these cytokines were increased further in cultures of NK cells and IL-2." (PMID 23982484, 2013). "Inclusion of lenalidomide in cultures containing 50 % neuroblastoma/monocyte CM prevented the suppression of IL-2-induced direct cytotoxicity, ADCC, and IFNγ secretion." (PMID 23982484, 2013). "We also show that IL-6, similar to the neuroblastoma/monocyte CM, significantly suppresses release of IFNγ by IL-2-stimulated NK cells." (PMID 23982484, 2013). "Anti-angiogenic integrin αv antagonist and antibody-IL-2 fusion protein induced tumor regression and dramatically decreased tumor vessel density in syngenic neuroblastoma model." (PMID 21876694, 2012). "Yu AL, Gilman AL, Ozkaynak MF, eta al.: Anti-GD2 antibody with GM-CSF, interleukin-2, and isotretinoin for neuroblastoma." (PMID 21929757, 2011). "Immunotherapy using tumour cells transduced with single-chain interleukin-12 (IL-12) protein has shown promise in murine models of neuroblastoma, an effect that was enhanced in combination with tumour-targeted interleukin-2 (IL-2) protein." (PMID 17595664, 2007). "Here we have compared the antitumour effect of fibroblasts and tumour cells transfected ex vivo to coexpress interleukin-2 (IL-2) and IL-12 in a syngeneic mouse model of neuroblastoma." (PMID 17595664, 2007). "These levels had previously proved therapeutic for neuroblastoma in A/J mice and also compared well with levels of IL-2 and IL-12 expression reported with adenoviral vectors." (PMID 17595664, 2007).
neuroblastoma (continued). "A vaccine for neuroblastoma featuring the expression of both a cytokine and a chemokine transgene (IL-2 and lymphotactin) by a single human neuroblastoma cell line is a recent example of this strategy." (PMID 15969754, 2005). "In conclusion, in this study, we have shown that coexpression of IL-2 and IL-12 offers improved antitumour immunity in a murine model of neuroblastoma and provides a potential approach for the treatment of neuroblastoma." (PMID 12771934, 2003). "Human IL-2 secretion by human neuroblastoma cell lines reached a peak 24–48 h post-transfection in both cell lines, with IMR-32 cells expressing 349.7±5.5 ng 24 h−1 10−6 cells and SHSY5Y cells 14.3±1.25 ng 24 h−1 10−6 cells." (PMID 12771934, 2003). "Initially, transfection of human and mouse neuroblastoma cell lines resulted in high expression levels of biologically active IL-2 and IL-12 in vitro." (PMID 12771934, 2003). "We report here the improved antitumour effect of two cytokines, interleukin-2 (IL-2) and interleukin-12 (IL-12), when coexpressed by neuroblastoma cell lines." (PMID 12771934, 2003). "Natural Killer cells treated with a combination of IL-2 and IL-12 exhibit enhanced in vitro cytolytic activity and lyse neuroblastoma cells and human osteosarcoma cells more efficiently." (PMID 12771934, 2003). "The biological activity of IL-2 and IL-12 produced by the neuroblastoma cells was tested on PHA-stimulated peripheral blood lymphocytes." (PMID 12771934, 2003). "Peripheral blood mononuclear cells from neuroblastoma patients showed increased cytotoxic activity when activated in vitro with both cytokines than with IL-2 or IL-12 alone." (PMID 12771934, 2003). "Neuroblastoma patients are overall young and mostly below the age of 10, and this may therefore support the effective expansion of γδ T cells with IL-2 alone in our study." (PMID 40897471, 2025). "The results of our study indicate that DB ± IL-2 is more effective than NAXI+GM-CSF in the treatment of patients with relapsed or refractory neuroblastoma in the bone or bone marrow who have demonstrated a partial response, a minor response or stable disease following previous therapy." (PMID 40940820, 2025). "Building up on the role of ADCC in treatment outcome, a phase III trial combining Ch14.18 with IL-2, GM-CSF and retinoic acid for neuroblastoma showed superiority to the standard of care chemotherapy considering both overall survival (73.2%) and progression free survival (56.6%) at 5 years." (PMID 37670947, 2023). "With the exception of ID2, all the other immune genes (CD8a, IL2, IL7R, IL6, ID3, and CXCR3) were also highly expressed in low-risk neuroblastoma patients further confirming the significance of these immune genes in neuroblastoma cases with favorable outcomes." (PMID 36068918, 2023). "Additionally, two immune monitoring studies in neuroblastoma observed that IL-2 cycles increased eosinophil counts." (PMID 38087370, 2023). "Indeed, glycolytic flux was efficiently engaged in NK cells from neuroblastoma patients with unexpectedly higher basal glycolysis and glycolytic capacity in response to IL2 compared to pediatric controls." (PMID 36276144, 2022). "We noted that the IL-2 response at day 9 was only modest against these leukemia targets, but given strong responses against neuroblastoma and strong IL-2 response by fourth rechallenge, the TE9 binder was therefore selected for further optimization of CAR-T function." (PMID 36159778, 2022). "The study concluded that adding IL-2 to dinutuximab beta did not improve outcomes of patients with high-risk neuroblastoma but was associated with more toxicity." (PMID 35327550, 2022). "Neuroblastoma cells induced Il2 release only in CAR T cells utilizing CD28 signaling." (PMID 33801448, 2021).
neuroblastoma (continued). "Moreover, the combination of another murine anti-GD2 antibody (ch14.G2a) with intravenous IL-2 showed a partial antitumor response in one neuroblastoma patient (out of 33 patients) and a decrease in neuroblastoma cells in the bone marrow of three patients." (PMID 34884452, 2021). "It was later observed that the response to treatment in patients with neuroblastoma was improved when GM-CSF, IL-2, and the biologic disease modifier isotretinoin (13-cis-retinoic acid, a retinoid derivative of vitamin A) are combined with anti-GD2 mAbs to enhance ADCC." (PMID 32733795, 2020). "For example, addition of subcutaneous IL-2 to immunotherapy with chimeric anti-GD2 monoclonal antibody dinutuximab beta did not improved outcomes in patients with high-risk neuroblastoma." (PMID 32560387, 2020). "The efficacy of IL2 in neuroblastoma therapy has also been investigated." (PMID 32560387, 2020). "In the TBJ neuroblastoma model, the effect of transduced IL-27 could be further enhanced by the administration of IL-2, which led to the complete regression of neuroblastoma metastases." (PMID 28255204, 2017). "Hu14.18-IL2, also known as “APN301” is a fusion protein consisting of IL2 linked to a humanized monoclonal antibody that recognizes the GD2 disialoganglioside expressed on neuroblastoma cells." (PMID 28574434, 2017). "Finally, in a cohort of neuroblastoma patients we identified a strong correlation between WASp, IL-2, and patient survival." (PMID 27477778, 2016). "Finally, in cohorts of neuroblastoma patients and patients with diffuse large B cell lymphoma we identified a strong correlation between WASp, IL-2, and patient survival." (PMID 27477778, 2016). "The same group later showed that an allogeneic tumor vaccine combining transgenic human lymphotactin with IL-2 in patients with advanced and refractory neuroblastoma led to 2-fold expansion of CD4+ T cells and 3.5-fold expansion of NK cells, inducing a more potent immunologic and clinical response." (PMID 26587548, 2015). "In a study by Bowman and coworkers, adenovector-mediated transfer of the IL-2 gene into autologous neuroblasts in patients with relapsing neuroblastoma led to a clinically effective antitumor immune response mediated by both helper and cytotoxic T lymphocytes in some patients." (PMID 26587548, 2015). "However, PBMCs obtained from the same patient following 4 weeks of IL2 infusions mediated much higher ADCC of neuroblastoma cells, and the addition of IL2 in vitro dramatically boosted the anti-GD2 mAb-mediated ADCC." (PMID 26284063, 2015). "Addition of anti-disialoganglioside (GD2) chimeric mAb ch14.18, IL-2, and GM-CSF immunotherapy to 13-cis-retinoic acid improved event-free survival (EFS) for patients with high-risk neuroblastoma, but approximately 40 % still relapsed during or after this therapy." (PMID 23982484, 2013). "Additionally, a Phase I-II study is open for pediatric patients with advanced neuroblastoma using repeated immunization with gene-modified, IL-2/XCL1-secreting neuroblastoma tumor cell vaccines." (PMID 24967094, 2013). "Similarly, we had demonstrated previously an increased cytotoxicity of haploidentical unstimulated NK cells with concomitant DCs and monocytes against neuroblastoma compared to IL-2 stimulated NK cells." (PMID 23730623, 2013). "Because of these clinical and preclinical effects, we hypothesized that lenalidomide also could prevent the suppression of IL-2 activation of NK cells by neuroblastoma/monocyte CM, IL-6, and TGFβ1." (PMID 23982484, 2013). "Furthermore, the IL-2 stimulation led to a consistent increase in NK cell killing activity against a neuroblastoma cell line and the leukemic cell line K562." (PMID 22096557, 2011). "We have demonstrated previously that Neuro-2A murine neuroblastoma cells could be transfected simultaneously with two plasmids using a synthetic vector system to express high levels of both IL-2 and single-chain IL-12." (PMID 17595664, 2007).
neuroblastoma (continued). "The aim of the current study was to use this nonviral vector to deliver genes encoding IL-2, IL-12, or a combination of these cytokine genes, to neuroblastoma cells in an attempt to develop a therapeutic cellular vaccine." (PMID 12771934, 2003). "Also, the combination of IL-2 and IL-12, when expressed by murine neuroblastoma cells, was capable of eradicating established tumours and exhibited a greater antitumour effect than either cytokine alone." (PMID 12771934, 2003). "Study of the immunophenotypic features of each patient's neuroblastoma cells before induction of MRD may be valuable in determining the likely effect of IL2 in predicting disease reactivation." (PMID 8494726, 1993). "However, this was discontinued, since a recent randomized phase III trial of patients with high-risk neuroblastoma showed that the addition of IL-2 to anti-GD2 antibody therapy did not improve outcome and increased treatment toxicity." (PMID 38087370, 2023). "Cell-based immunotherapy using NK cells for children with relapsed neuroblastoma has also been explored, particularly after the report of a child with relapsed neuroblastoma who received haploidentical donor NK cells combined with temozolomide, topotecan, and IL-2 and had a complete response." (PMID 30384486, 2018). "TILs from neuroblastoma lesions expanded on average 15-fold during the pre-REP phase, and 200-fold during the second 2 wk of expansion with αCD3 and IL-2 (REP phase), resulting in a total expansion of ∼1,500-fold." (PMID 40897471, 2025). "In neuroblastoma models, anti-GD2 WT IL-2 immunocytokines enhanced antitumor efficacy and immune cell infiltration when delivered intratumorally, compared with intravenous injection or unconjugated IL-2 treatment." (PMID 41568361, 2025). "Historically, numerous anti-GD2 mAbs have been evaluated for clinical use in neuroblastoma cases including 3F8, humanized 3F8 (naxitamab), 14.G2a, DIN, hu14.18K322A, humanized 14.18 fused with interleukin-2, and dinutuximab beta." (PMID 37760578, 2023). "Primary T cells expressing GD2.CARs cultured in H.S. medium exhibited a superior killing ability and a stronger secretion of IL-2 and IFN-γ against GD2+ neuroblastoma cell line CHLA-255 in vitro compared to those cultured in a regular medium." (PMID 36882513, 2023). "The combination of IL-2, IL-12, and IL-18 also resulted in potent antitumor activity against different cell lines like Ewing sarcoma (A673), rhabdomyosarcoma (RH30), and neuroblastoma (SH-SY5Y)." (PMID 36429001, 2022). "A phase I/IB study assessed the combination of IL-2 and murine anti-GD2 antibody 14G2A in patients with recurrent neuroblastoma." (PMID 34796286, 2021). "For patients with refractory neuroblastoma, treatment with ZOL and IL-2 indeed resulted in an increased amount of peripheral γδ-T cells, but unfortunately the expansion rate was still too low to be therapeutically effective." (PMID 34575700, 2021). "The effect of hADSCs on activation of peripheral blood mononuclear cells (PBMCs) and proliferation and viability of SH-SY5Y neuroblastoma cells after co-culture with native hADSCs, hADSCs-BFP or hADSCs-IL2 on plastic and Matrigel was evaluated." (PMID 32560387, 2020). "Our lab previously showed that peripheral blood mononuclear cells (PBMCs) obtained from cancer patients pre-IL2 treatment had low levels of ADCC against a neuroblastoma cell line, even in the presence of both anti-GD2 mAb and IL2." (PMID 26284063, 2015). "When combined with granulocyte-macrophage colony-stimulating factor (GM-CSF) and interleukin-2 after autologous HSCT, a statistically significant improvement in progression-free survival was observed in neuroblastoma." (PMID 25977601, 2015). "We discovered that lenalidomide, at a clinically achievable concentration, prevented the suppression of IL-2-mediated activation of NK cell cytotoxicity, ADCC, and IFNγ secretion by neuroblastoma/monocyte CM." (PMID 23982484, 2013).